PIGM (phosphatidylinositol glycan anchor biosynthesis class M)
Description:
Catalytic subunit of the glycosylphosphatidylinositol-mannosyltransferase I complex which catalyzes the transfer of the first mannose, via an alpha-1,4 bond from a dolichol-phosphate-mannose (Dol-P-Man) to a 2-acyl-6-alpha-D-glucosaminyl-1-(1-radyl,2-acyl-sn-glycero-3-phospho)-1D-myo-inositol (glucosaminyl acyl phosphatidylinositol, GlcN-(acyl)PI) intermediate to generate 2-acyl-6-(alpha-D-mannosyl- (1->4)-alpha-D-glucosaminyl)-1-(1-radyl,2-acyl-sn-glycero-3-phospho)- 1D-myo-inositol (also termed H2) and participates in the sixth step of the glycosylphosphatidylinositol-anchor biosynthesis.
Synonyms: GPI-MT-I; PIG-M
Tractability: Antibody: UniProt predicts a signal peptide or a membrane-spanning region.
Gene: Protein-coding gene on chromosome 1 (160,024,953 to 160,031,990, reverse strand). Ensembl gene ENSG00000143315.
Subcellular location: Endoplasmic reticulum membrane
Pathways (Reactome):
Metabolism of proteins: Synthesis of glycosylphosphatidylinositol (GPI)
Gene Ontology:
Molecular function: dol-P-Man:GlcN-acyl-PI alpha-1,4-mannosyltransferase activity; protein binding; mannosyltransferase activity; alpha-1,4-mannosyltransferase activity; GPI mannosyltransferase activity
Biological process: GPI anchor biosynthetic process
Cellular component: endoplasmic reticulum membrane; glycosylphosphatidylinositol-mannosyltransferase I complex; membrane
Genetic constraint (gnomAD): Loss-of-function variants: 11 observed, 18.68 expected, observed/expected ratio (o/e) 0.59, 90% interval 0.37 to 0.98. The upper end of that interval is the gene's LOEUF score, 0.98, which puts it in group 4 of 6, group 1 being the genes least tolerant of losing a copy. Missense variants: 506 observed, 553.59 expected, observed/expected ratio (o/e) 0.91, 90% interval 0.85 to 0.98. Synonymous variants: 216 observed, 233.2 expected, observed/expected ratio (o/e) 0.93, 90% interval 0.83 to 1.04.
Gene-disease validity (ClinGen):
ClinGen rates the evidence that PIGM causes each of these diseases.
hypercoagulability syndrome due to glycosylphosphatidylinositol deficiency (autosomal recessive): Limited. The combination of a propensity for venous thrombosis and seizures has been reported in two unrelated kindreds.
Homologues: Orthologues: macaque PIGM (97% identical), rat Pigm (91% identical), mouse Pigm (90% identical), rabbit PIGM (87% identical), guinea pig PIGM (87% identical), dog PIGM (75% identical), zebrafish pigm (52% identical), tropical clawed frog pigm (51% identical), Caenorhabditis elegans pigm-1 (40% identical), Drosophila melanogaster PIG-M (36% identical).
Diseases named in the same sentence as PIGM in open-access papers:
PIGM is named in the same sentence as 13 diseases in open-access papers, as found by Europe PMC text mining. Sharing a sentence is not in itself a finding about the gene and the disease. The quoted sentences say what the papers report.
paroxysmal nocturnal haemoglobinuria (2 papers, 2009 to 2015). "The first disorders to be described in association with deficiencies of the GPI-anchor biosynthesis pathway were paroxysmal nocturnal haemoglobinuria (PNH), caused by somatic mutations in PIGA, in haemopoietic cells, and inherited GPI deficiency caused by a hypomorphic promoter mutation in PIGM." (PMID 26293662, 2015).
Venous thrombosis (2 papers, 2020 to 2022). Formation of a blood clot (thrombus) inside a vein, causing the obstruction of blood flow. "A hypomorphic promoter variant in PIGM leads to inherited GPI deficiency, characterized by a propensity to venous thrombosis and absence seizures." (PMID 32612635, 2020).
anaplastic ependymoma (1 paper, 2022). Anaplastic ependymoma is a rare, malignant type of ependymoma that most often arises in the supratentorial region of the brain of children and young adults and that manifests with variable symptoms including headaches, nausea, vision impairment, memory loss and difficulty walking. "The mutational profile of the primary tumor and metastases from a patient with recurrent anaplastic ependymoma yielded candidate mediators of metastatic spread, including CUL9 and PIGM." (PMID 36010837, 2022).
Macrocephaly (1 paper, 2024). Occipitofrontal (head) circumference greater than 97th centile compared to appropriate, age matched, sex-matched normal standards. "Interestingly, macrocephaly has been reported in patients with mutations in PIGA, PIGC, and PIGM, which are involved in the initial stages of GPI anchor biosynthesis." (PMID 40225942, 2024).
multiple myeloma (1 paper, 2013). "As an example, we have shown for PIGM, transcription of this enzyme is closely correlated with its translation in distinct multiple myeloma cell lines." (PMID 24386263, 2013).
myeloma (1 paper, 2013). "Transcriptional data for PIGM expression were validated by qRT-PCR and for the corresponding PIG-M protein expression by Western blotting using the myeloma cell lines KMS-12-BM and OPM-2 with low and high PIGM gene expression, respectively." (PMID 24386263, 2013). "PIGM, one of the most highly overexpressed genes in the comparison between normal and malignant plasma cells, and contributing to the classifier distinguishing between both, was also one of the overexpressed genes in the myeloma group with the adverse cytogenetic markers." (PMID 24386263, 2013). "Of these genes, PIGM expression, encoding for the enzyme phosphatidylinositol glycan anchor biosynthesis protein M (PIG-M), was significantly higher in myeloma cell samples with 1q21-gain or del13q14 and significantly lower in hyperdiploid myeloma cell-samples." (PMID 24386263, 2013).
infection (1 paper, 2024). The state of being infected such as from the introduction of a foreign agent such as serum, vaccine, antigenic substance or organism. "When SARS-CoV-2 infects the respiratory tracts and lungs, mucosal immunity is expected to suppress infection establishment through the transcytosis and secretion of dIgA and pIgM across the lung epithelial cells by pIgR, together with other immune mechanisms." (PMID 39066171, 2024).
PIGM also shares sentences with these, for which no sentence is quoted: genetic diseases (2 papers); cerebellar ataxia (1); CHIME syndrome (1); Cognitive impairment (1); glycosylphosphatidylinositol deficiency (1); tumor (1).